LYN (LYN proto-oncogene, Src family tyrosine kinase)
Diseases named in the same sentence as LYN in open-access papers (continued):
Sharing a sentence is not in itself a finding about the gene and the disease.
preeclampsia (2 papers, 2012 to 2013). Preeclampsia is a hypertensive disorder of pregnancy that is characterized by new-onset hypertension with proteinuria presenting after 20 weeks of gestation, and depending on mild or severe forms may initially present with severe headache, visual disturbances, and hyperreflexia. "FLT1, LEP, INHA and ENG genes were identified according to the literature, however, we also found other genes as FLNB, INHBA, NDRG1 and LYN highly significant but underexplored during normal pregnancy or preeclampsia." (PMID 24219996, 2013). "However, there are not articles of PDIA3, TBK1 or LYN related with preeclampsia." (PMID 22873350, 2012).
adenosquamous carcinoma (1 paper, 2016). A carcinoma composed of malignant glandular cells and malignant squamous cells. "IHC results showed that high LYN expression in samples had positive correlation with FIGO stage (P <0.05) and tumor grade, but obvious relation was found neither with the patient age (P >0.05) nor with tumor type (squamous cell carcinoma versus adenosquamous carcinoma, P >0.05." (PMID 27690342, 2016).
Amoebiasis (1 paper, 2019). "In addition, the up-regulated DEGs were significantly enriched in 12 pathways such as NF-kappa B signaling pathway including LYN, LY96, CCL4, CD14; ECM-receptor interaction pathway including CD44, COL6A3, COL1A2, FN1 and Amoebiasis pathway including COL1A2, ITGB2, CD14, FN1." (PMID 31355054, 2019).
ankylosing spondylitis (1 paper, 2022). An autoimmune chronic inflammatory disorder characterized by inflammation in the vertebral joints of the spine and sacroiliac joints. "Immunohistochemical staining was performed for LYN in five patients with ankylosing spondylitis and three patients with spinal fracture." (PMID 36263434, 2022).
Arthritis (1 paper, 2023). Inflammation of a joint. "Later, they demonstrated that HCK, FGR, LYN are critical in generation of in vivo inflammatory environment in autoantibody-induced arthritis and other inflammation mouse models." (PMID 37463911, 2023).
brain cancer (1 paper, 2014). A primary or metastatic malignant neoplasm affecting the brain. "The kinase CSNK1E had been previously associated only with non-brain cancers, while HIPK2, LYN, and EPHB4 have been suggested as targets for anti-tumor therapies." (PMID 25236784, 2014).
cutaneous mastocytosis (1 paper, 2015). Cutaneous mastocytosis is a term referring to a group of diseases characterized by abnormal accumulation and proliferation of skin mastocytes. "Data from a phase 2 study in patients with systemic or cutaneous mastocytosis (N = 25) treated with the KIT/LYN kinase inhibitor masitinib, however, demonstrated an ORR of 56.0 % and modest improvements in symptoms and quality-of-life measurements after 12 weeks of treatment." (PMID 26002753, 2015).
diabetes (1 paper, 2022). "Circulating EVs from people with diabetes carry increased levels of specific phosphorylated kinases (i.e., AKT1, GSK3B, LYN, MAP2K2, MYLK, and PRKCD) and could potentially distribute activated kinases systemically." (PMID 35628588, 2022).
diffuse large B-cell lymphoma (1 paper, 2025). "Notably, LYN was specifically upregulated in the Pfeiffer cell line, a diffuse large B-cell lymphoma (DLBCL) model driven by aberrant B cell receptor (BCR) signaling." (PMID 41035678, 2025).
duodenal adenocarcinoma (1 paper, 2023). A carcinoma that arises from glandular epithelial cells of the duodenum. "Proteogenomics reveals LYN amplification at the chromosome 8q gain functioned in the transmit from intraepithelial neoplasia phase to infiltration tumor phase via MAPK signaling, and illustrates the DST mutation improves mTOR signaling in the duodenal adenocarcinoma stage." (PMID 36991000, 2023).
endometrial cancer (1 paper, 2011). Primary or metastatic malignant neoplasm involving the endometrium (mucous membrane that lines the endometrial cavity). "LYN was of particular interest because as a kinase, it is "druggable" and might provide a therapeutic opportunity for targeting endometrial cancer." (PMID 22040021, 2011).
gastric tumor (1 paper, 2015). "Moreover, as for SRC, LYN may also have a role in gastric tumor invasiveness, metastasis, and thus aggressiveness." (PMID 26460485, 2015).
head and neck cancer (1 paper, 2023). A primary or metastatic malignant neoplasm affecting the head and neck. "Targeting LYN, STAT3, and NF-κB showed potential for inhibiting cell motility and tumor growth in EGFRvIII-expressing head and neck cancers 42,43." (PMID 37416766, 2023).
hyperlipidemia (1 paper, 2025). "In this study, HCK, LYN, WAS, and PTK2B were identified as hub genes using Maximal Clique Centrality, holding significant implications for future research on hyperlipidemia." (PMID 41446394, 2025).
Immunodeficiency (1 paper, 2022). Failure of the immune system to protect the body adequately from infection, due to the absence or insufficiency of some component process or substance. "Consistent with this notion, whereas loss-of-function mutations of BTK result in immunodeficiency, loss-of-function mutation of LYN rather results in autoimmunity." (PMID 35440579, 2022).
invasive breast carcinoma (1 paper, 2010). A carcinoma that infiltrates the breast parenchyma. "As observed within the invasive breast cancer specimen, SRC and LYN were the highest-expressed SFK members in non-malignant breast tissue." (PMID 20717116, 2010).
liver disease (1 paper, 2023). "In contrast to Patients 1 and 3 with the truncating mutations, Patient 2 with the LYN missense mutation, p.Y508F, did not develop liver disease suggesting that the truncating mutations that eliminate the 5 terminal amino acids may confer more severe disease." (PMID 36932076, 2023).
mantle cell lymphoma (1 paper, 2023). Mantle cell lymphoma is a rare form of malignant non-Hodgkin lymphoma affecting B lymphocytes in the lymph nodes in a region called the ``mantle zone''. "Phosphorylation of several kinases downstream of the BCR such as SYK, LYN and BTK have been noted in primary mantle cell lymphoma (MCL) cells, suggesting constitutively activated BCR signaling in MCL." (PMID 37954584, 2023).
meningioma (1 paper, 2025). A generally slow growing tumor attached to the dura mater. "The T cells in meningioma showed five additional drug-target kinases that were significantly increased in expression compared to VS (CSF1R, LYN, ABL, MAP2K1, and BRAF), whereas VS had only one drug-target kinase, KDR." (PMID 41437121, 2025).
mental disorder (1 paper, 2024). A disease that has its basis in the disruption of mental process. "Emerging evidence suggests that LYN dysregulation may contribute to the pathophysiology of certain mental disorders, primarily through its involvement in immune modulation and neural signaling pathways." (PMID 39684694, 2024).
myeloid leukemia (1 paper, 2020). A clonal proliferation of myeloid cells and their precursors in the bone marrow, peripheral blood, and spleen. "In myeloid leukemia, sfRON but not flRON physically interacted with the intracellular tyrosine kinase LYN to drive cell proliferation in a PI3K/AKT-independent manner." (PMID 32272784, 2020).
osteosarcoma (1 paper, 2022). A usually aggressive malignant bone-forming mesenchymal neoplasm, predominantly affecting adolescents and young adults. "And LYN, TNC, TGFB2, IGFBP1were up-regulated in the osteosarcoma tissue samples, while IGFBP4, TAGLN, SERPINE1, ANPEP were down-regulated." (PMID 35665757, 2022). "However, the relative expression levels of LYN, TNC, TGFB2, and IGFBP1 were significantly higher in the osteosarcoma group compared with the normal group (P < 0.05)." (PMID 35665757, 2022).
renal cell carcinoma (1 paper, 2018). "VEGFA, KDR, LYN, CD3E and LOX are among those factors that are not identified by DIAMOnD but have a renal cell carcinoma associated literature support." (PMID 29861861, 2018).
staphylococcus aureus infection (1 paper, 2020). An infectious process in which the bacteria Staphylococcus aureus is present. "Then, LYN, FCGR3A, and FCGR3B are involved in “module 1” of the subnetwork, in which GO functional annotation is enriched in inflammatory response and immune response, and KEGG pathway enrichment analysis is enriched in staphylococcus aureus infection, phagosome, and osteoclast differentiation." (PMID 32733557, 2020).
triple-negative breast carcinoma (1 paper, 2020). An invasive breast carcinoma which is negative for expression of estrogen receptor (ER), progesterone receptor (PR), and human epidermal growth factor receptor 2 (HER2). "Besides, the ULK1 activator LYN-1604, which can induce autophagy-related cell death through the ULK complex, shows significant anticancer activity in triple-negative breast cancer." (PMID 33344463, 2020).
unipolar depression (1 paper, 2024). "RNA editing modifications were analyzed using a panel of eight genes (CAMK1D, GAB2, IFNAR1, KCNJ15, LYN, MDM2, PDE8A, PRKCB) that we previously identified and whose editing combinations were suggested as biomarkers to distinguish BD from unipolar depression and subcategories of BD patients." (PMID 39684694, 2024).
tumor (52 papers, 2006 to 2026). "Accordingly, and in line with the literature, strong correlation was found between the relative immune fraction and the levels of FGR and the SRC-B sub-family (except LYN), suggesting their expression to be associated with the tumor immune microenvironment." (PMID 39390250, 2024). "Then, we analysed expression of the same set of genes in the set of tumour cell primary cultures previously analysed for Lyn conditional allele recombination and Lyn gene and LYN protein expression." (PMID 38149669, 2024). "LYN was involved in tumor mutation, correlated with the regulation of oncogenic genes, and also showed a significant positive correlation with PD-L1." (PMID 35186945, 2021). "At single cell sequencing level, LYN was abundantly expressed by tumor associated macrophages and T cells." (PMID 35186945, 2021). "Here, we report that reduced SRC and LYN methylation was associated with advanced stage GC, deeper tumor invasion and with lymph node or distant metastasis." (PMID 26460485, 2015). "Additionally, ADA is linked to RGS4 and LYN, highlighting its role in purine metabolism and immune response modulation in the tumor microenvironment." (PMID 39267843, 2024). "However, some tumours retained strong LYN expression, suggesting incomplete recombination in vivo; furthermore, some tumours with wild-type alleles showed very low levels of expression." (PMID 38149669, 2024). "LYN stratified patients’ survival in the Xiangya cohort and was also significantly associated with infiltrating immune cell types and inflammatory activities in the tumor microenvironment." (PMID 35186945, 2021). "Interestingly, in a LYN−/− mouse model, loss of LYN function induces an increase of myeloid progenitors leading to tumor development." (PMID 30428571, 2018). "Variation in the behaviour of tumours across a cohort, and indeed in multiple tumours from a single mouse, could result from partial floxed allele recombination in Lynfl/wt or Lynfl/fl mice, or from suppression of LYN expression by other mechanisms in Lynwt/wt mice." (PMID 38149669, 2024). "The results showed that co-treatment of COR and LYN significantly reduced the tumor volume of xenografts established from MDA-MB-231 and MDA-MB-453 cell lines." (PMID 40764992, 2025). "Leukemic cells activate inflammatory pathways in BMSCs, such as AKT, LYN, PKCβII, and NF‐ĸB, resulting in increased tumor survival." (PMID 40809351, 2025). "The upregulation of SMO (smoothened) and LYN suggests that ciBMSCs exhibit features of chondrocytes and CAFs, potentially contributing to tumor progression by remodeling the extracellular matrix or secreting cytokines." (PMID 40809351, 2025). "LYN staining was assessed both qualitatively and semi-quantitatively using a histoscore approach based on the strength of staining and the area of the tumour stained." (PMID 38149669, 2024). "Future studies to test our model that the activity of LYN-dependent, cell-intrinsic signalling pathways results in an anti-tumour immune response will likely require single-cell transcriptomic analysis or a similar approach." (PMID 38149669, 2024). "There was a significant reduction in LYN staining in the cells of Lynfl/fl tumours compared to that in Lynwt/wt tumours (Mann–Whitney test, P=0.002) and Lynfl/wt tumours (Mann–Whitney test, P=0.0344)." (PMID 38149669, 2024). "COLO357, the cell model with the highest LYN activity, is known to represent a tumor with high Src dependency." (PMID 38739359, 2024). "We identified 51 upregulated genes in the tumor samples derived from the patients with relapse within 60 months, participating primarily in inflammation and innate immune responses (e.g., LYN, LY96, ANXA1)." (PMID 38256136, 2024). "Although these results showed that, overall, there was a correlation between LYN staining of a tumour and the genotype of the animal the tumour came from, they also highlighted the variability in staining between tumours of the same genotype." (PMID 38149669, 2024).
tumor (continued). "Stroma-derived LYN even enhances cancer cell survival, shedding new light on its role as resistance mediator for tumor cells under therapy stress." (PMID 38739359, 2024). "Histoscore quantitation of LYN staining was carried out for the neoplastic epithelial-like tumour cells." (PMID 38149669, 2024). "Accordingly, we performed IHC staining on mouse tumor sections to detect P38α, LYN, p70S6K and their phosphorylated proteins." (PMID 38988047, 2024). "ADAM8 has been revealed as one of three potential tumor markers, whereby the others are LYN and S100A9, for metastasis and tumor reoccurrence in colon cancers." (PMID 36910158, 2023). "The tumor-forming capacity and growth size were reduced after silencing LYN; however, they were enhanced by LYN overexpression." (PMID 37416766, 2023). "This study extends our previous observations regarding the regulatory role of LYN in the tumor microenvironment." (PMID 36899005, 2023). "In summary, CC12 showed potential to reach the brain area and then executed its anti-GBM capacity by downregulating LYN-mediated tumor progression and initiating apoptosis pathways." (PMID 37416766, 2023). "We further used DAVID to search for those genes from the predicted target genes that are related to tumor, and found the target genes of LYN, RASAL2, FZD4, and GNG2 for further study." (PMID 35174106, 2022). "LYN is a member of the Src family tyrosine kinases and operates as a pro-oncogene in the progression of human tumor." (PMID 34514167, 2021). "Out results indicated that miR-496/LYN inhibited the tumor growth by suppressing the AKT/mTOR signaling pathway." (PMID 34514167, 2021). "LYN overexpression blocked the inhibition of tumor cell growth, as well as the inhibition of AKT/mTOR signaling pathway induced by miR-496." (PMID 34514167, 2021). "These upregulated sites included two clinical drug targets annotated as Src-family kinases (HCK and LYN), which were reported to promote tumor malignancy in NSCLC43." (PMID 33953186, 2021). "LYN was mostly localized in hyperplastic blood vessels region that created a permissive environment for tumor growth." (PMID 35186945, 2021). "The GSEA results in GO and KEGG further confirmed that LYN correlated with immune suppressive activity and tumor proliferation in TCGA and CGGA." (PMID 35186945, 2021). "LYN knockdown markedly impaired growth of mouse Brca1 tumor-derived cells in monolayer culture and in three-dimensional (3D) culture conditions on Matrigel." (PMID 30590041, 2018). "Because LYN blockade effectively suppressed tumor cell growth in vitro, we next evaluated the effects of blocking LYN activity in vivo." (PMID 30590041, 2018). "In vivo study, overexpression LYN promoted tumor growth, meanwhile knockdown LYN inhibited tumor growth." (PMID 27690342, 2016). "We further analyzed the prognostic value of LYN expression by subgrouping patients with respect to sex, smoking history, and tumor histology using Kaplan-Meier analysis." (PMID 27756880, 2016). "Reduced percentage of SRC, LYN and CKB methylation were associated with advanced stage, deeper tumor invasion, and the presence of lymph node and distant metastases (p < 0.05, for all comparisons)." (PMID 26460485, 2015). "Increased protein and mRNA expression of SRC and LYN and reduced CKB expression were associated with advanced stage, deeper tumor invasion, and the presence of lymph node and distant metastases (p < 0.05, for all comparisons)." (PMID 26460485, 2015). "A gradual decrease in the percentage of SRC and LYN methylation was observed corresponding to the tumor stage (p < 0.008, for most of the comparisons; Mann-Whitney test followed by Bonferroni correction)." (PMID 26460485, 2015). "As for SRC and LYN, MYC immunoreactivity or elevated mRNA expression was previously associated with late onset, advanced stage, deeper tumor extension and the presence of metastasis." (PMID 26460485, 2015).